S1PR1 (sphingosine-1-phosphate receptor 1)
Diseases named in the same sentence as S1PR1 in open-access papers (continued):
Sharing a sentence is not in itself a finding about the gene and the disease.
cystic fibrosis (2 papers, 2022 to 2025). Autosomal recessive disorder caused by pathogenic variants in the CFTR gene (cystic fibrosis transmembrane conductance regulator), which encodes a chloride and bicarbonate channel expressed in epithelial cells, and follow the diagnosis criteria. "In a cohort of patients with cystic fibrosis, two SNVs in the S1PR1 gene are associated with Pseudomonas aeruginosa infection, again indicating the translational relevance of multigenetic background studies in animal organisms." (PMID 35886916, 2022).
diabetic nephropathy (2 papers, 2017 to 2021). "In the diabetic nephropathy mouse S1PR1 agonist, the renal tubular epithelial cell barrier and relaxation function are improved; meanwhile, the damaged epithelial cells are impaired, all of which improve kidney microcirculation." (PMID 34751249, 2021). "After combination with S1PR1-5, S1P mainly activates ERK, SAPK/JNK, p38-MAPK, and ROCK/Rho signaling pathways to regulate the proliferation of islet β cells, promote insulin secretion, reduce the complications of large vessels, and relieve diabetic nephropathy." (PMID 34751249, 2021). "In addition, work done by Awad and colleagues demonstrated that independent S1PR1 activation using selective and non-selective S1PR1 agonists such as SEW2871 and FTY720 reduces early stage diabetic nephropathy." (PMID 29186855, 2017).
esophageal cancer (2 papers, 2020). A primary or metastatic malignant neoplasm involving the esophagus. "Liu demonstrated that S1PR1 can regulate the proliferation and apoptosis of esophageal cancer cells." (PMID 33029266, 2020).
follicular thyroid cancer (2 papers, 2018 to 2019). "Several studies reported that S1P–increased HIF1α expression was abolished by S1PR1/S1PR3 inactivation or S1PR3 silencing in liver hepatocellular carcinoma cells and thyroid follicular carcinoma cells, respectively." (PMID 31383843, 2019).
glomerulonephritis (2 papers, 2020). A renal disorder characterized by damage in the glomeruli. "However, Mir223 deficiency exacerbated glomerulonephritis in B6-Mir223−−-Faslpr/lpr mice by facilitating the infiltration of S1PR1+CD4+ T cells into kidney tissues." (PMID 33574820, 2020).
H1N1 influenza (2 papers, 2017 to 2023). "S1PR1 agonist CYM5442 markedly suppressed the exaggerated inflammatory response upon H1N1 influenza challenge even in the early H1N1 influenza phase, providing in vivo protection with reduced mortality." (PMID 37746079, 2023).
hemorrhagic stroke (2 papers, 2023 to 2024). A stroke caused by a bleed on the brain. "Siponimod, a new selective modulator of S1PR1 and S1PR5 with a short half-life and a better safety profile, has gained considerable attention as an immunomodulatory agent for the treatment of ischemic or hemorrhagic stroke in animals." (PMID 37191423, 2023).
HIV-1 infection (2 papers, 2023). The type species of lentivirus and the etiologic agent of acquired immunodeficiency syndrome (AIDS). "To determine whether HIV-1 infection causes changes in S1PR1 expression in the human thymus, we utilized Human Immune System (HIS)-Rag2−/−γ-chain−/− mice implanted with human fetal thymus/liver (thy/liv) tissue." (PMID 37762169, 2023). "Our data show that S1PR1 is upregulated in human thymocytes during intrathymic HIV-1 infection at two time points post-infection as well as in mature thymocyte populations during systemic HIV-1 infection." (PMID 37762169, 2023). "Further studies will be needed to understand the roles of IFN-α, IFN-β, and IFNAR1/2 in modulating the expression of S1PR1 in the context of HIV-1 infection." (PMID 37762169, 2023). "Therefore, there appears to be a mechanism that overrides the requirement for the downregulation of CD69 for S1PR1 to be expressed in our models of HIV-1 infection of the human thymus as well as systemic infection." (PMID 37762169, 2023).
infarct (2 papers, 2023). "Using SEW2871 to pharmacologically activate S1PR1 notably reduces infarction size and increases myocardial contractility post-infarction in mice joined by parabiosis." (PMID 37176067, 2023).
intracerebral hemorrhage (2 papers, 2019). A cerebrovascular disorder characterized by bleeding into one or both cerebral hemispheres including the basal ganglia and the cerebral cortex. "More recently, whole-transcriptome analysis in patients with intracerebral hemorrhage correlated to neuroinflammation revealed a connection between DDX24 and Sphingosine 1-phosphate receptor 1 that is a target of the treatment of relapsing MS with Fingolimod." (PMID 31805175, 2019).
ischemia reperfusion injury (2 papers, 2017 to 2018). Adverse functional, metabolic, or structural changes in ischemic tissues resulting from the restoration of blood flow to the tissue (reperfusion), including swelling; hemorrhage; necrosis; and damage from free radicals. "Multiple studies demonstrated a protective effect in ischemia-reperfusion injury using fingolimod (agonist for S1PR1, S1PR3, S1PR4, and S1PR5) in different organs including the heart." (PMID 28596734, 2017).
kidney injury (2 papers, 2022 to 2025). Trauma to the kidney. "A S1PR1 agonist, SEW2871, also ameliorated I/R kidney injury by reducing the infiltration of neutrophils/macrophages and proinflammatory molecules (TNF-α, P-selectin, E-selectin and intercellular adhesion molecule-1; ICAM-1)." (PMID 35409370, 2022).
malaria (2 papers, 2020). Malaria is a serious and sometimes fatal disease caused by a parasite that commonly infects a certain type of mosquito which feeds on humans. "We also observed the DARC gene, which encodes the Duffy antigen receptor for human malaria, was significantly co-expressed with VCAM1, S1PR1 and ELTD1 in multiple tissues." (PMID 32652930, 2020). "Although albumin too function as S1P acceptor, the observation of increased albumin in cerebrospinal fluid impairing BBB function of Malawian children with CM and reported S1PR1 internalization upon albumin-S1P binding precludes its utility in therapeutics use in malaria." (PMID 32923406, 2020). "It is possible that FTY720 by down regulating S1PR1 during late stage infection may lead to breach of BBB which may facilitate effective delivery of artesunate to central nervous system (CNS) for execution of immune-protective response against malaria." (PMID 32923406, 2020). "However, the effect of S1P and S1PR1 signaling in human malaria has not been investigated in terms of NO production and subsequent clinical outcome." (PMID 32923406, 2020).
memory impairment (2 papers, 2016 to 2024). "RNA-Seq analysis and gain/loss-of-function study revealed that S1P/S1PR1 signaling is a determinant for vulnerability to chronic pain-related memory impairment." (PMID 39699949, 2024). "Overall, these findings suggest that the variation in structural plasticity of the hippocampal DG underlies susceptibility and insusceptibility to chronic pain-related memory impairment, and it is modulated by S1P/S1PR1 signaling." (PMID 39699949, 2024). "Consequently, knockdown of S1PR1 in the CCI-treated mice led to more susceptible mice (up to 86%) to memory impairment." (PMID 39699949, 2024). "Memory impairment-susceptible mice exhibited decreased S1PR1 expression in the hippocampal DG." (PMID 39699949, 2024). "Overall, these findings suggest that DG S1PR1 may govern the susceptibility of memory impairment by regulating actin polymerization via interaction with ITGA2." (PMID 39699949, 2024). "In the present study, by employing an array of techniques including rodent-based behavioral tests, RNA-Seq, imaging, pharmacological and biochemical approaches, we elucidated a pivotal role of S1PR1 within the hippocampal DG in the context of chronic pain-associated memory impairment." (PMID 39699949, 2024). "In summary, our study develops a paradigm for separating the susceptible and unsusceptible subgroups to chronic pain-induced memory impairment and delineates the key role of S1P/S1PR1 signaling in vulnerability to memory impairment." (PMID 39699949, 2024). "Conversely, overexpression of S1PR1 or pharmacological administration of an S1PR1 agonist in the DG, promoted an unsusceptible phenotype, thereby averting the onset of memory impairment, and alleviated morphological abnormalities in DGCs." (PMID 39699949, 2024). "Taken together, these findings raised the possibility that S1P/S1PR1 may participate in the occurrence of chronic pain-related memory impairment." (PMID 39699949, 2024). "Additionally, we also overexpressed DG S1PR1 and noticed that it promoted mice to be unsusceptible to memory impairment, similarly irrelevant to sensitivity to thermal pain stimuli." (PMID 39699949, 2024). "We then investigated whether a continuous 14-day local infusion of SEW2871 in the DG from day 7 post CCI could inhibit the reduction of S1PR1 expression and confer insusceptibility to memory impairment." (PMID 39699949, 2024). "S1PR1 knockdown in the dentate gyrus (DG) induces memory impairment." (PMID 39699949, 2024). "Overexpression of S1PR1 in the dentate gyrus (DG) rescues chronic pain-induced memory impairment." (PMID 39699949, 2024). "We then examined whether overexpression of S1PR1 in the DG influences chronic pain-related memory impairment according to behavioral paradigms of Y-maze and MWM tests." (PMID 39699949, 2024). "We knocked down DG S1PR1 and found that the loss of S1PR1 in the DG induced more susceptible mice to memory impairment without affecting pain threshold." (PMID 39699949, 2024). "Consistently, TEM images and Golgi staining revealed that continuous activation of S1PR1 in the DG significantly prevented the occurrence of defective synaptic plasticity, indicating that activation of S1PR1 in the DG confers insusceptibility to memory impairment." (PMID 39699949, 2024). "In the Y-maze and MWM tests, overexpression of S1PR1 in CCI-treated mice significantly improved the spatial memory formation by promoting insusceptibility to memory impairment (up to 82%), but had no obvious effects on Sham-treated mice." (PMID 39699949, 2024).
myeloid leukemia (2 papers, 2022 to 2025). A clonal proliferation of myeloid cells and their precursors in the bone marrow, peripheral blood, and spleen. "S1PR1 inhibits JNK signaling, promotes apoptosis in myeloid leukemia cells, and promotes cell proliferation by inhibiting ROS production, accelerating elimination, and activating ERK signaling." (PMID 35854395, 2022).
nasopharyngeal carcinoma (2 papers, 2017 to 2024). A carcinoma arising from the nasopharyngeal epithelium. "Likewise, miR-133b has been predicted to target S1PR1 which caused suppression of cell proliferation in nasopharyngeal carcinoma cells." (PMID 39315290, 2024). "On the other hands, in the case of nasopharyngeal carcinoma (NPC) cells, endogenous S1PR1 protein expression was effectively modulated due to over-expression of miR 133b." (PMID 39315290, 2024).
Nephroblastoma (2 papers, 2015 to 2019). An embryonal neoplasm characterized by the presence of epithelial, mesenchymal, and blastema components. "In Wilms tumor (also called nephroblastoma), S1PR1 stimulates migration and invasion through PI3K and the Rac pathway, which has promigratory properties." (PMID 31807117, 2019).
osteoarthritis (2 papers, 2015 to 2024). A noninflammatory degenerative joint disease occurring chiefly in older persons, characterized by degeneration of the articular cartilage, hypertrophy of bone at the margins and changes in the synovial membrane. "Patients with active RA have decreased circulating S1P and decreased expression of synovial EC S1PR1 transcripts compared with patients with osteoarthritis." (PMID 38855867, 2024). "High expression of S1PR1 in RA synovial tissue was observed in the synovial lining, vascular endothelial cells, and mononuclear cells when compared to osteoarthritis and normal synovial tissues." (PMID 26556954, 2015).
osteosarcoma (2 papers, 2021 to 2022). A usually aggressive malignant bone-forming mesenchymal neoplasm, predominantly affecting adolescents and young adults. "The expression levels of LPAR1, LPAR6, S1PR1, and S1PR3 were relatively high in the osteosarcoma tumor tissues." (PMID 34302117, 2021).
skin inflammation (2 papers, 2019 to 2023). "We demonstrated that myeloid, specifically macrophage, S1PR1, has protective effects in IMQ-induced skin inflammation in mice by an underlying, reciprocal regulation of neoangiogenesis and neolymphangiogenesis." (PMID 31357710, 2019). "However, we observed that myeloid-specific deletion of S1PR1 not only attenuated neolymphangiogenesis, but also strongly induced angiogenesis, which is reported to act as a pro-inflammatory in skin inflammation." (PMID 31357710, 2019). "Thus, our study adds to the better understanding the role of S1P in skin inflammation via S1PR1 on macrophages, and assigns to them a regulatory function in affecting neoangiogenesis and neolymphangiogenesis." (PMID 31357710, 2019). "It is not surprising that in skin inflammation S1PR1 is a critical regulator of angiogenesis, due to the fact that it has been demonstrated to be the first G protein-coupled receptor required for blood vessel formation." (PMID 31357710, 2019).
uveal melanoma (2 papers, 2023 to 2025). A melanoma derived from melanocytes of the uveal tract. "These uveal melanoma patients exhibit an increase in the expression of classic and well-documented hypoxia-dependent genes such as PDGFB, LOXL2, VEGF, ANGPT2, KDR, and S1PR1." (PMID 40000790, 2025).
uveitis (2 papers, 2020 to 2023). An inflammatory process affecting a part of or the entire uvea. "To examine whether downregulation of S1pr1 under conditions of LXA4 deficiency can be detected in uveitis-relevant T cells, we assessed S1pr1 expression in CD4+ T cells from inguinal lymph nodes of EAU-challenged Alox5-/- and WT mice by RT-PCR." (PMID 32118582, 2020).
acute graft versus host disease (1 paper, 2015). A syndrome of immunologically mediated tissue damage that may occur following an allogeneic transplant, usually affecting the skin, liver, and GI tract. "In addition, S1PR1-selective agonist CYM inhibits acute graft-versus-host disease by reducing macrophage infiltration." (PMID 26324256, 2015).
adenoma (1 paper, 2020). A neoplasm arising from the epithelium. "Our current observations revealed: i) a not significant modulation of S1P levels in CRC patients; ii) higher expression of S1PR1 among the receptors in the normal mucosa; iii) a marked decrease only of S1PR2 in primary CRC already at an early phase (adenoma) of tumor development." (PMID 33225975, 2020).
bladder tumors (1 paper, 2021). "Clinical bladder tumor histological analysis shows that high expression of S1PR1 is associated with poor patient prognosis." (PMID 34503284, 2021). "The main distribution of S1PR1 in bladder tumors was analyzed in microarray and single cell sequencing databases with well-defined histological patterns." (PMID 34503284, 2021).
bone osteosarcoma (1 paper, 2019). A usually aggressive malignant bone-forming mesenchymal neoplasm arising from the bone. "In this demonstration, we used the human bone osteosarcoma epithelial cell line (U2OS) modified to express green fluorescent protein (GFP)-tagged S1P1, or sphingosine-1-phosphate-receptor 1, which translocates from the plasma membrane to the nucleus in the presence of specific ligands." (PMID 31366957, 2019).
brain cancer (1 paper, 2020). A primary or metastatic malignant neoplasm affecting the brain. "Furthermore, we found that low S1PR1 expression was associated with a poor prognosis in patients with soft tissue, blood, and brain cancers." (PMID 32799825, 2020).
cervical cancer (1 paper, 2026). A primary or metastatic malignant neoplasm involving the cervix. "Our findings suggest that SpHK1/S1P/S1PR1 may serve as a promising target for the treatment of cervical cancer." (PMID 41513624, 2026). "The SpHK1/S1P/S1PR1 pathway, which is modulated by glycolytic and lipid metabolic reprogramming, may serve as a potential therapeutic target for cervical cancer treatment." (PMID 41513624, 2026). "Importantly, inhibition of the S1P/S1PR1 signaling pathway down-regulates the expression of S100A8/A9 and suppresses the growth of HPV-KI cells and xenograft derived from cervical cancer patient." (PMID 41513624, 2026).
chronic heart failure (1 paper, 2020). "Since genetic EC‐S1pr1 overexpression in vitro can inhibit cardiomyocyte hypertrophy and myofibroblast accumulation, we next tested whether pharmacological activation of S1pr1 has a beneficial effect on pathological cardiac remodelling during chronic heart failure." (PMID 31854513, 2020).
Cirrhosis (1 paper, 2025). A chronic disorder of the liver in which liver tissue becomes scarred and is partially replaced by regenerative nodules and fibrotic tissue resulting in loss of liver function. "S1PR1 promotes both neovascularization and decreased cell-to-cell adhesion, two of the pathological hallmarks necessary for oncogenesis and metastasis, although this gene has never been directly implicated as an oncogene for HCC or a cirrhosis associated mutation." (PMID 40040391, 2025).
classical Hodgkin lymphoma (1 paper, 2024). "For example, in the Hodgkin/Reed–Sternberg (HRS) cells of classical Hodgkin lymphoma (cHL), S1P has been shown to activate phosphatidylinositide 3-kinase (PI3-K) signaling, an effect that is mediated by the increased expression of S1PR1 and the decreased expression of S1PR2." (PMID 38339325, 2024).
diabetic cardiomyopathy (1 paper, 2023). Diabetic cardiomyopathy is a disorder of the heart muscle in people with diabetes. "Additionally, sphingosine 1-phosphate receptor 1 activation in T cells leads to fibrosis in normoglycemic conditions but exacerbates fibrosis in a model of STZ-induced diabetic cardiomyopathy." (PMID 36776877, 2023).
disc degeneration (1 paper, 2023). "Similarly, a downregulated gene S1pr1 and its ligand S1P are reported to have an anti-inflammatory function in the disc and is downregulated during human disc degeneration suggesting an inflammation-permissive niche in ank mutants." (PMID 37468461, 2023).
encephalitis (1 paper, 2025). An acute inflammatory process affecting the brain parenchyma. "Consequently, we proposed that targeting the broader S1P metabolic pathway, rather than focusing solely on S1PR1 signaling, may offer more effective therapeutic strategies in treating EV-A71-associated encephalitis." (PMID 39692504, 2025). "Thus, targeting S1P-metabolism rather than S1PR1 signaling might ameliorate EV-A71-associated encephalitis." (PMID 39692504, 2025).
endometriosis (1 paper, 2022). The growth of functional endometrial tissue in anatomic sites outside the uterine body. "In endometriosis lesions, the high expression of S1P and S1PR1 leads to the migration of endometrial stromal cells, proliferation and angiogenesis, indicating that they play a role in the pathogenesis of endometriosis." (PMID 36524127, 2022). "According to our findings, the use of S1PR1 as a pharmacological target for endometriosis provides a reasonable further application for FTY720 (Fingolmod)-based therapy." (PMID 36524127, 2022).
gastric ulcer (1 paper, 2014). An ulcerated lesion in the mucosal surface of the stomach. "Our results show that CA can decrease the expression of S1P and its receptors, including S1Pr1 and S1Pr3, to relieve inflammation problems to relieve the formation of gastric ulcers." (PMID 24454691, 2014).
Hashimoto thyroiditis (1 paper, 2023). An autoimmune disorder caused by the production of autoantibodies against thyroid tissue. "Activated STAT3 amplifies the expression of inflammatory cytokines and S1PR1, which further exacerbates the development of Hashimoto thyroiditis." (PMID 37858140, 2023). "In CD4 + T cells in Hashimoto thyroiditis, increased SphK1 produces more S1P, which activates the S1PR1-JAK2-STAT3 and S1PR1-mTOR-STAT3 pathways." (PMID 37858140, 2023).